PKD1 (polycystin 1, transient receptor potential channel interacting)
Diseases named in the same sentence as PKD1 in open-access papers (continued):
Sharing a sentence is not in itself a finding about the gene and the disease.
Hypertension (continued). "The PROPKD score uses urologic event and/or hypertension before the age of 35, genetic mutation (truncating PKD1, non-truncating PKD1 or PKD2) and gender to determine the risk of progression to ESRD." (PMID 30764782, 2019). "Our finding that PKD1 mutations confer an ≈8.5-fold increased risk of LVH, independent of hypertension, age, sex and anaemia, strongly supports the hypothesis that intrinsic mechanisms related to polycystin-1 dysfunction directly impact myocardial structure or function." (PMID 41195291, 2025). "Secondly, the study population was small and heterogeneous in terms of age, presence of arterial hypertension, the extent of renal involvement, genetic background (TSC1, TSC2, TSC2+PKD1), and treatment with mTOR inhibitors." (PMID 34912759, 2021). "During hypertension, a number of GPCR agonists is elevated such as endothelin and several catecholamines, which activate PKD1 in a PKC-dependent manner and via phosphorylation at Ser744/748, i.e., the canonical PKD1 pathway." (PMID 29930945, 2018). "Specifically, we evaluated the time to endpoints of hypertension, ESRD, and death in participants with the PKD1 genotype." (PMID 29035198, 2018). "PKD2 is usually significantly milder than PKD1 with development of ESRD at a later age and a lower prevalence of arterial hypertension and urinary tract infections." (PMID 29479522, 2017). "This prognostic model utilizes genetic and clinical data to identify key factors, including gender, hypertension before age 35, the first urologic event before age 35, PKD2 mutation, and non-truncating or truncating PKD1 mutation." (PMID 41153257, 2025). "Very briefly summarized the PROPKD score is based on four variables: gender, type of genetic variant (truncating PKD1 variant, non-truncating PKD1 variant, PKD2 variant), hypertension before the age of 35 years, first urologic event before the age of 35 years." (PMID 34882278, 2021). "Left ventricular hypertrophy (LVH, prevalence 30%) was significantly associated with PKD1 mutations (PKD1 non-truncating versus PKD2 adjusted P-value = .011; PKD1 truncating versus PKD2 adjusted P-value = .011), independent of hypertension, age, sex and anaemia (adjusted OR 8.5, P = .008)." (PMID 41195291, 2025). "However, his TKV and htTKV values were significantly smaller than two of our PKD1 cohorts used to monitor our proband (PKD1 patients ≤ 40 years, and PKD1 with BMI < 25), but not smaller than PKD1 without hypertension." (PMID 35327948, 2022). "Likewise, a similar tendency seems to exist for PKD1 genotype, hypertension, and haematuria, but none of these variables reaches statistical significance (p=0.128, 0.184 and 0.245, respectively)." (PMID 32158561, 2020).
Kidney Cyst (40 papers, 2011 to 2025). Abnormal fluid filled sac within the kidney, either acquired or congenital. "In fact, kidney cyst formation, caused by mutation of cilia residing receptor polycystin 1/2 (PKD1/2) or DAs protein CEP164, can be mitigated by inhibition of cyclin-dependent kinases." (PMID 40483459, 2025). "In patients with the diagnosis of PKHD1, ALG8, and GANAB variants, kidney cysts tend to be less destructive than PKD1 and PKD2 with relatively preserved kidney contours." (PMID 35778421, 2022). "In one patient (ID109.2) with postnatal kidney cysts and early-onset hypertension, a likely pathogenic PKD1 variant was identified in trans with a class 3 variant possibly explaining congenital disease manifestation by way of disease modification." (PMID 32398770, 2020). "Kidney cyst expansion in mice, whether in settings of decreased or increased Pkd1 expression, was consistently associated with elevated levels of cAMP, known to promote growth, proliferation, and secretion in cultured human ADPKD epithelial cells." (PMID 41122971, 2025). "In addition to these 7 patients, 1 with the PKD1 pathogenic variant had a sibling with simple kidney cyst." (PMID 39291187, 2024). "Most ADPKD patients carry mutations on the PKD1 or PKD2 genes, though kidney cysts appear earlier and progress more rapidly with PKD1 mutations." (PMID 38956234, 2024). "Of 157 patients, 7 had parents with simple kidney cyst (1 with the IFT140 pathogenic variant, 3 with the PKD1 or PKD2 pathogenic variant, 1 with the OFD1 pathogenic variant, and 2 without pathogenic variants)." (PMID 39291187, 2024). "Typically, PKD1 patients have greater htTKV than PKD2 patients, and although PKD1 and PKD2 kidneys increase in size at the same rate, PKD1 patients have 40% more detectable kidney cysts." (PMID 38156331, 2023). "The observed activation of YAP in human ADPKD and mouse Pkd1 kidney cysts, and now in jck kidneys, raises the possibility that the sensing of external signals is linked to YAP regulation." (PMID 36326820, 2022). "We expect that Pkd2 mutants would develop kidney cysts at older ages based on evidence from Pkd1 models, but severe liver findings precluded further aging." (PMID 34962918, 2021). "Previous studies have demonstrated that further postnatal reductions in PKD1 (or PKD2) dose are required for kidney cyst formation, which can be induced by DNA damage, and activation of the DNA damage response pathway." (PMID 32724471, 2020). "In this model, PKD1 expression was reduced at a transcriptional and translation level, macroscopically visible kidney cysts were detectable from 5 months of age and by 24 months of age these cysts began to deform the normal kidney shape." (PMID 32630605, 2020). "Previous work demonstrated that the human ADPKD kidney cyst phenotype can be reproduced in mice 14 weeks after conditional ablation of nephron-localized Pkd1 or Pkd2." (PMID 29443690, 2018). "Consistent with previous reports, we find that repression of either Pkd1 or Pkd2 results in obvious kidney cysts within two months after removal of doxycycline." (PMID 29443690, 2018). "Using a Pkd1 conditional knockout mouse, we demonstrate that subtly altering the timing and extent of Pkd1 deletion can have a significant impact on the origin and severity of kidney cyst formation." (PMID 27356569, 2016). "Three children had TSC2/PKD1 contiguous gene deletion syndrome, which may provide a slight bias to the results in terms of overall CKD risk and kidney cyst burden." (PMID 38483608, 2024). "In this study, we explored whether MNPs can target cystic kidney tubules and whether rapamycin-encapsulated MNPs can slow kidney cyst growth in Pkd1 knockout (KO) mice." (PMID 38956234, 2024). "Kidney cyst formation ensues when PKD1 dosage falls below a critical threshold." (PMID 35965273, 2022). "Our studies also clarify the role of PKD1 in the continual expansion and growth of kidney cysts." (PMID 35965273, 2022).
Kidney Cyst (continued). "In addition, this study found that hypermethylation of the PKD1 gene body (exon 43) in ADPKD patient samples, negatively correlated with the PKD1 gene expression, suggesting that epigenetic silencing of the PKD1 gene is involved in kidney cyst development." (PMID 35847973, 2022). "Kidney cyst formation occurs when PKD1 dosage falls below a critical threshold." (PMID 35965273, 2022). "Patients with Bardet-Biedl syndrome may also present with ADPKD-like kidney cysts, which may be caused by the involvement of BBS1 and 3 in ciliary trafficking of polycystin 1 (the PKD1 gene product)." (PMID 33677691, 2022). "Thus, although now only the PKD1 gene has been identified as the cause of the disease in cats, several studies found cases of animals with kidney cysts and a wild-type genotype of the PKD1 gene." (PMID 34822642, 2021). "Similarly, liver cysts were detected earlier than kidney cysts in an adult mouse model of Cre-mediated Pkd1 deletion In our model, Jnk deletion suppressed hepatic cysts." (PMID 34962918, 2021). "The onset of kidney cyst development in adult mice following conditional inactivation of Pkd1 or the intraflagellar transport protein kinesin, KIF3a (required for cilia formation), progresses well into adulthood, in analogy to the late progression of ADPKD in humans." (PMID 29443690, 2018). "Mutations in PKD1 and PKD 2 genes (encoding for polycystin 1 (PC1) and polycystin 2 (PC2)) lead to the formation and progressive expansion of kidney cysts which ultimately cause kidney enlargement and distortion of renal architecture, thus leading to kidney failure." (PMID 28346513, 2017). "RNA expression profiling of ADPKD and Pkd1–/– kidney cysts compared with healthy kidney tissue supports the targeting of the RhoA-YAP-cMyc axis, but wider profiling could be useful to identify other pathways to target at specific timepoints in cystogenesis or for particular genotypes." (PMID 33392209, 2020). "Here, we report the generation of a Pkd1‐linked, inducible mouse model that represents the genetic and phenotypic characteristics of human ADPKD, and demonstrate that subtle differences in the timing and extent of Pkd1 loss cause significant changes in the pattern of kidney cyst growth." (PMID 27356569, 2016). "In humans, MCP1 expression increases in PKD1 kidneys, and indeed, high levels of uMCP1 in ADPKD patients have been found, which correlated with kidney cyst size, and were suppressed after tolvaptan treatment." (PMID 36342644, 2023). "Pkd1-/- embryos develop rapidly progressive kidney cysts during embryogenesis, with null mutant kidneys showing no cysts at E14.5 and marked cystic changes by E17.5." (PMID 21518438, 2011). "PKD1 and PKD2 variants are linked to ADPKD regardless of the presence or absence of PLD, while PRKCSH and SEC63 variants are always associated with ADPLD without kidney cysts." (PMID 37761895, 2023).
kidney failure (39 papers, 2008 to 2026). An acute or chronic condition that is characterized by the inability of the kidneys to adequately filter the blood. "Both 31-year-old women, born at 33 weeks because of preeclampsia, inherited a truncating PKD1 variant from their mother, in a family with a history of kidney failure before the age of 50 years." (PMID 41502815, 2026). "Generally, mutations in PKD2 are associated with a later onset and a slower progression to renal failure compared to those in PKD1." (PMID 41294622, 2025). "Patients with pathogenic PKD1 variants have a more severe form of disease with faster rates of progression to kidney failure than patients with pathogenic PKD2 variants." (PMID 39883360, 2025). "Variations in PKD1 are generally associated with a more severe disease course and an earlier onset of kidney failure compared to those in PKD2." (PMID 40565535, 2025). "Genetic factors, particularly pathogenic variants in PKD1 and PKD2, have been strongly associated with disease severity, with truncating PKD1 mutations leading to earlier onset of kidney failure." (PMID 41294622, 2025). "ADPKD is the most common genetic cause of renal failure and arises mainly due to mutations in PKD1 gene, which encodes polycystin-1, a multidomain integral membrane protein." (PMID 40457431, 2025). "ADPKD is characterized by progressive bilateral kidney cysts, and most individuals with PKD1 mutations have kidney failure by age 70 (the mean age of onset is 54.3 years)." (PMID 39323690, 2024). "ADPKD, a common aetiology of kidney failure, is caused by heterozygous PKD1 or PKD2 mutations." (PMID 35965273, 2022). "This study found that people with PKD1 ADPKD carrying additional damaging genetic variants in the PKD1 gene, progress to kidney failure at an earlier age." (PMID 39883360, 2025). "PKD1 p.(Arg3277Cys) homozygotes have been reported to develop adult-onset PKD with kidney failure or transplantation at ages 62, 75, and 50 consistent with this dosage-dependent model." (PMID 40225160, 2023). "PKD1RC/null mice developed severe cystic enlargement that rapidly progressed to kidney failure around 20 days-of-age, whereas PKD1 RC/RC manifested as a slowly progressive cystic disease." (PMID 34671066, 2021). "To characterise the inflammatory response, we looked at the level of transcripts for the macrophage marker Adgre1 (F4/80) and found this to be significantly less abundant in double KO compared to Pkd1 KO mice at kidney failure." (PMID 31038742, 2019). "At 10 weeks after DCVC and kidney failure, however, we observed a reduction in injury marker expression together with reduced fibrosis and macrophage infiltration in Pkd1 KO mice compared with double KO." (PMID 31038742, 2019). "The effect of using subsets of the affected individuals (s1, s2, s3 and s4) and different cutoff values in the screening of the known causative genes PKD1 and PKD2 for a family with renal failure." (PMID 19399176, 2009). "The error possibilities calculated using genotyping error simulation method in screening known causative genes PKD1 and PKD2 for a family with renal failure with the genotype data of patient s1 and s4." (PMID 19399176, 2009). "Heterozygous, pathogenic loss-of-function variants in either PKD1 or PKD2 are the primary cause of typical ADPKD, which is characterised by development of progressive macroscopic kidney cysts that cause massively enlarged kidneys and kidney failure." (PMID 41006799, 2026). "Furthermore, in contrast to previous studies suggesting that PKD1 and PKD2 are the most common genetic causes of kidney failure, our findings indicate that among Bedouins, COL4A3 variants are the predominant genetic etiology." (PMID 40303201, 2025). "Likewise, the expression of transforming growth factor beta‐1 (Tgfb1) was significantly less in double KO compared to Pkd1 KO mice at 10 weeks and showed a similar trend at kidney failure." (PMID 31038742, 2019).
kidney failure (continued). "Interestingly, at kidney failure, Kim1 expression was significantly higher in Pkd1 KO mice compared to double KO." (PMID 31038742, 2019). "Disease caused by mutations in PKD1 is usually correlated with a worse outcome and kidney failure at a mean age of 56 years (55.6 years if the genetic variant is truncating, versus 67.9 years if non-truncating), as opposed to the PKD2 phenotype with a mean age of 77 years at onset of kidney failure." (PMID 39574911, 2024). "Notably, PKD1 mutations account for 85–90% of the cases and are associated with significantly more severe diseases, whereas 10–15% of ADPKD cases are attributed to mutations in PKD2, and those patients have a later onset of symptoms and a slower rate of progression to renal failure." (PMID 40136708, 2025). "The characteristic phenotype of patients with TSC2/PKD1 contiguous gene syndrome is the presence of early-onset polycystic kidney lesions, which tend to grow more rapidly than those in patients with classical TSC, resulting in kidney failure in the teenage years." (PMID 39323690, 2024). "Indeed, Axin2, Cd44, Ccnd1 and to certain extent Myc, showed significantly lower expression in double KO compared with Pkd1 KO mice, both at 10 weeks after DCVC and at kidney failure, suggesting a reduced activation of the canonical Wnt signalling in the absence of Fjx1." (PMID 31038742, 2019).
breast cancer (31 papers, 2007 to 2024). A primary or metastatic malignant neoplasm involving the breast. "In summary, loss of PKD1 has been widely accepted as a marker of aggressiveness in various cancer types and model systems, including its correlation with poorer prognosis in breast cancer patients." (PMID 37293129, 2023). "In particular, in breast cancer, the loss of PKD1 and increase in PKD3 expression in invasive ductal carcinomas underscores the existence of isoform-specific functions." (PMID 37293129, 2023). "In highly invasive breast cancer, loss of PKD1 appears to promote invasion and metastasis, whereas PKD2 and upregulated PKD3 positively influence proliferation, chemoresistance and metastasis." (PMID 37293129, 2023). "In breast cancer all three isoforms (PKD1, PKD2 and PKD3) have been implicated in regulating cancer cell survival and proliferation during tumor formation." (PMID 30555634, 2018). "We previously reported that overexpression of PKD1 confers estrogen independence to ER+ breast cancer cells and is associated with a poorer prognosis in ER+ tamoxifen-treated breast tumors." (PMID 29796183, 2018). "In the context of cancer progression, the loss of PKD1 and its effect has been studied most extensively in breast cancer." (PMID 26848698, 2016). "For example, in breast cancer and gastric cancer the loss of PKD1 has been shown to be mediated through hypermethylation of the PRKD1 promoter." (PMID 26848698, 2016). "As seen in the case of breast cancer, the loss of PKD1 in gastric cancer occurs due to hypermethylation of the PRKD1 promoter." (PMID 26848698, 2016). "Suppression of PKD1 expression was found to be associated with enhanced cellular invasion via modulation of multiple matrix metalloproteinases (MMPs) in breast cancer cells." (PMID 25149539, 2014). "The deregulation of PKD1 expression is associated with various cancers including prostate and breast cancer." (PMID 25149539, 2014). "By comparing control to PKD1-knockdown cells in an orthotopic animal model, we demonstrate that local invasion and breast cancer metastasis to the lung are specific to loss of PKD1 and can be blocked with decitabine." (PMID 23971832, 2013). "Taken together, using different methods, we show that the methylation status of the gene promoter directly correlates not only with the loss of PKD1 expression but also with the invasive potential of breast cancer cells." (PMID 23971832, 2013). "In summary, our analysis of patient data indicates that decrease or loss of PKD1 expression in human breast cancer is due to hypermethylation of the PRKD1 promoter." (PMID 23971832, 2013). "They further suggest that the loss of PKD1 expression increases the malignant potential of breast cancer cells." (PMID 19243594, 2009). "Invasive behaviour in breast cancer cell lines has been linked to matrix metalloproteinases (MMPs), so we also determined if PKD1 regulates the expression and activity of these enzymes." (PMID 19243594, 2009). "PKD1 expression is associated with breast cancer drug-resistance properties." (PMID 35805075, 2022). "It has been reported that PKD1 expression is gradually reduced during breast cancer progression, which could be directly associated with hypermethylation of PKD1 promoter." (PMID 30619291, 2018). "This loss of PKD1 in breast cancer is associated with tumor invasiveness." (PMID 26848698, 2016). "Interestingly, among the PKD1-positive cell lines tested (n = 8), a strong PKD1 expression was associated with a high invasive phenotype, whereas lower expression levels were found in weakly invasive breast cancer cells." (PMID 25287328, 2014). "This implies that loss of PKD1 expression during breast cancer progression may contribute to mammary neoplasia and lead to the acquisition of metastatic characteristics." (PMID 23971832, 2013).